BRD4 (bromodomain containing 4)
Diseases named in the same sentence as BRD4 in open-access papers (continued):
Sharing a sentence is not in itself a finding about the gene and the disease.
cancer (continued). "Along with the disruption of BRD4 expression, an obvious proliferation arrest was observed in the tumor cells, suggesting the feasibility of ENCTACs for inhibiting cancer growth." (PMID 36516252, 2022). "In cancer cells, inhibition of bromodomain-containing protein 4 (BRD4), a transcriptional regulator that promotes tumor growth, induces ferroptosis by increasing ferritinophagy." (PMID 35563704, 2022). "For instance, human bromodomain and extraterminal domain (BET) protein BRD4 (bromodomain-containing protein 4) plays key roles in regulating innate immune response, DNA break repair, and cancer." (PMID 36372880, 2022). "Pharmacologic inhibition of BRD4 has been widely studied as a potential therapeutic target in cancers." (PMID 35399501, 2022). "Bromodomain-containing protein 4 (BRD4) plays a pivotal role in transcriptional regulation and is a feasible drug target in cancer cells." (PMID 35159127, 2022). "BRD4 is an epigenetic regulator known to have a role in cancer super-enhancer assembly and transcriptional control." (PMID 36114560, 2022). "Targeting BRD4 in cancer has gained increased interest due to its multiple roles in transcriptional regulation." (PMID 35182012, 2022). "BRD4 is an effective drug target affected by various cancers, whereas VHL is usually recruited by PROTACs to degrade various targets in vitro and in vivo." (PMID 35958877, 2022). "In cancer cells, BRD4 can bind to Jagged-1 and NOTCH1 promoters, increasing the gene expression of both NOTCH components and thus leading to NOTCH pathway activation." (PMID 35215234, 2022). "ChIP-seq analysis shows RB knockdown increases BRD4 occupancy at genomic loci of genes enriched in cancer-related pathways including the GPCR-GNBIL-CREB axis." (PMID 36274096, 2022). "We treated cSCC cells with THZ1, a covalent inhibitor of CDK7, and JQ1, a specific inhibitor of BRD4, which both have been shown to selectively target SE-driven transcriptional programs in cancer." (PMID 36010973, 2022). "Taken together, these results signify strong dependence of these cancer cell lines on high expression of BRD4, indicating the potential therapeutic effect of BET family inhibition." (PMID 35832114, 2022). "In a subset of cancer cells, BRD4 inhibition results in R-loop accumulation, leading to cell death caused by transcription–replication collisions and DNA double-strand breaks during the S-phase." (PMID 34540900, 2021). "Yet the discovery of off target interactions with (bromodomain 4) BRD4 dampened the interest of XMD8-92 becoming a cancer therapeutic." (PMID 34456740, 2021). "A primary downstream target of BRD4 is MYC—a member of the myc family of transcription factors encoded by the proto-oncogene, which is frequently deregulated in cancer." (PMID 34681760, 2021). "After development of specific inhibitors targeting BET BDs, BET factors, especially Brd4, emerged as key regulators of transcription and as promising targets in the therapy of cancer and immunoinflammatory diseases." (PMID 34137374, 2021). "Recently, inhibition of BRD4, the chromatin reader, has been shown to specifically reduce the expression of myc in many different cancer types." (PMID 34073112, 2021). "They had proposed combing the inhibitors of CDK9 with those against BRD4 and cMYC to efficiently inhibit the proliferation and promote apoptosis of cancer cells." (PMID 34062779, 2021). "Further research has shown that JQ1, a brd4‐specific inhibitor, can break SEs of cancer stem cells, becoming a new target for cancer." (PMID 33336467, 2021). "Previously, it has been documented that BRD4 is capable of promoting cancer cell growth and invasion." (PMID 33500406, 2021). "This experiment strongly suggests that combined inhibition of CDK9 and BRD4 would be a useful strategy to combat cancers, which show high levels of MYC or other genes, whose expression is regulated by super-enhancers." (PMID 34359807, 2021).
cancer (continued). "Considering its high potency, selectivity for BD2, its small size (molecular weight = 286.24) and novel chemical scaffold, it is worth to be explored as a lead compound to inspire anti-cancer drug design and to treat other BRD4-related diseases." (PMID 33820450, 2021). "The abnormal manifestations of BET family members, especially BRD2 and BRD4, occur in various cancer types." (PMID 34540687, 2021). "BET inhibitors (BETi) targeting BET family of BD-containing proteins, including BRD4, have been considered as promising anti-cancer agents, but solid tumors, including CRC, are commonly resistant to BETi29,30." (PMID 34290255, 2021). "Recently, emerging evidence demonstrates that targeting Brd4 with small molecules shows great potential for cancer cell elimination." (PMID 34512660, 2021). "The BET protein family, including BRD2, BRD3, and BRD4, play an important role in cancer, among which BRD4 protein is involved in regulating cancer and inflammatory processes." (PMID 34943817, 2021). "In ccRCC, the PI3K–Akt signaling pathway is constitutively activated and shows critical role in cancer progression through regulating various targets, such as bromodomain-containing protein 4 (BRD4) and VHL–HIF pathway." (PMID 34244473, 2021). "Due to its central role in cell proliferation, apoptosis and transcription, BRD4 is considered a promising drug target for a number of human diseases including cancer, inflammation and cardiovascular diseases." (PMID 33820450, 2021). "Another CRBN-based against BET PROTAC named ARV-825 utilizes the link between OTX015 and E3 ligase CRBN to promote BRD4 degradation, eventually inhibiting the cancer cell progression." (PMID 35006464, 2021). "Inhibition of BRD4 shortcuts the communication between SEs and target promoters with a subsequent cell-specific repression of oncogenes to which cancer cells are addicted." (PMID 33916219, 2021). "Recently, targeting Brd4 with inhibitors has received considerable attraction and is broadly applied to a wide spectrum of disease from ongoing clinical trial on cancer to cardiovascular disease." (PMID 34512660, 2021). "As one of them, BRD4 can regulate various characteristics of cancer cells by adjustment of the expression and activity of cancer promoters, including drug resistance, apoptosis, cell transformation, proliferation, and invasion." (PMID 34956562, 2021). "The bromodomain and extraterminal (BET) protein family member BRD4 is a transcriptional and epigenetic regulator known to be involved in super-enhancer organization and transcriptional regulation in cancers." (PMID 33888130, 2021). "The members of the Bromodomains and Extraterminal (BET) family, comprising 4 genes BRD2, BRD3, BRD4 and BRDt (specific to testis and ovary), are important transcriptional and epigenetic regulators that play key roles in embryogenesis and cancer." (PMID 34208195, 2021). "The apoptotic effect of ARV was reported as a result of disrupting BRD4 that is expressed in various types of cancer." (PMID 34371697, 2021). "As an important transcriptional co-activator, BRD4 participates in several relevant processes in cancer, including DNA damage repair and cellular stress response." (PMID 34758842, 2021). "As a reader of protein lysine acetylation, BRD4 is largely acknowledged in cancer for its role in super-enhancer (SE) organization and oncogene expression." (PMID 33916219, 2021). "Pioneering studies have revealed that BRD4 is frequently overexpressed in multiple cancers including HNSCC, and promotes tumorigenesis, cancer cell proliferation, metastasis and drug resistance by elevating the expression of cancer drivers." (PMID 34261480, 2021).
cancer (continued). "Unlike inflammatory function, where both BRD2 and BRD4 were found to play a role in the regulation of cytokine genes, we show that when only BRD4 is perturbed do we see a significant reduction in the ability of NK cells to eliminate cancer target cells." (PMID 33717143, 2021). "Specifically, BRD4 has been recognized as a key regulator during cancer progression owing to its role in gene expression regulation, making it a popular cancer treatment target." (PMID 34175898, 2021). "CDK9 was involved in cancer progression through BRD4-dependent recruitment of p-TEFb involving transcription of the MYC gene, and that MYC is a proto-oncogene that controls cell growth and cell cycle processes." (PMID 35087760, 2021). "Due to its role in important cellular processes, BRD4 dysfunction can lead to the appearance of various human diseases, including inflammation, cardiovascular diseases and cancer." (PMID 33809005, 2021). "The bromodomain and extra-terminal (BET) protein family that includes BRD2, BRD3 and BRD4 is one of the best characterized families of epigenetic reader proteins in cancer." (PMID 34001289, 2021). "Cancer tissues were found to express higher levels of BRD4 as compared to normal tissues with reduced DNA methylation at specific BRD4 loci and reduced ferroptosis." (PMID 34226536, 2021). "It suggests that the utilization of both small molecule inhibitors and PROTACs makes targeted therapy of BRD4 an effective therapy in various cancer models." (PMID 35372800, 2021). "We initially examined BRD4 expression and found that BRD4 was the top-ranked gene in T-ALL cell lines relative to other types of cancer cell lines in CCLE samples." (PMID 33888130, 2021). "Ectopic expression of BRD4-targeting miRNA has proven to be a good strategy to inhibit BRD4-driven cancer progression." (PMID 33686960, 2021). "Targeting the epigenetic signaling molecule BRD4 effectively inhibits cancer cachexia and prolongs survival." (PMID 34876902, 2021). "On the other hand, AMPK can promote lysosome biogenesis via TFE3 or BRD4 and protect cancer cells under stresses." (PMID 33917483, 2021). "Collectively, these studies illustrate that BRD4 overexpression in cancer is likely due to enhanced mRNA transcription, abundance, and/or translation." (PMID 34540900, 2021). "Several BET bromodomain inhibitors that disrupt BRD4-dependent transcriptional activation are currently available as anti-cancer drug candidates 9,12,51." (PMID 34803511, 2021). "BRD4 plays a pivotal role in embryogenesis and cancer development, while its inhibitor is able to eliminate transcriptional activation of oncogenes and suppress tumor progression." (PMID 34579723, 2021). "In line with this, the anti-cancer activities (inhibition of growth, apoptosis) of BRD4 inhibitors have been shown to rely, at least in part, on transcriptional induction of the HEXIM1 gene, which allows recapture of P-TEFb into the 7SK inhibitory complex." (PMID 34146121, 2021). "Primarily, BRD4 was overexpressed in PTC specimens compared with that in normal tissues from patients and cell lines, suggesting the function of BRD4 in cancer progression." (PMID 33995657, 2021). "The results of the in vitro biophysical analysis prompted us to test BRD4 dimerization in human cancer cells." (PMID 34754068, 2021). "Involvement of BRD4 in DNA damage checkpoint activation and DNA repair sets the stage for new cancer therapy approaches using combinations with DNA damaging compounds." (PMID 33803654, 2021). "These agents disrupt the binding of BRD4 to acetylated chromatin, and inhibit growth and induce apoptosis in a variety of cancers, including hematologic malignancies and solid tumors." (PMID 33888130, 2021). "In particular, Trametinib-treated cancer cells showed de novo enhancer formation near the DDR1 gene that were enriched for BRD4 (bromodomain-containing protein 4) binding, which promoted a drastic increase in DDR1 expression." (PMID 34461089, 2021).
cancer (continued). "Significantly, BRD4 has been reported to promote expression of many transcription factors with roles in cancer development and progression such as Myc." (PMID 34001289, 2021). "PROTACs have shown the capability of degrading specific Bromodomains like BRD2 and BRD4 that play a key role in cancer progression." (PMID 33086530, 2020). "The accumulating evidence from these diverse data suggest that BRD4 plays a critical role in the transcription initiation and elongation of several genes promoting cell proliferation and cancer progression." (PMID 32218352, 2020). "BET proteins, especially Brd4 deregulated and this has been involved in diverse diseases, such as cancer formation and progression." (PMID 35746919, 2020). "Of note, according to The Cancer Genome Atlas database, BRD4 gene is amplified in approximately 10% of HGSOCs, laying the groundwork for BETis to represent a potentially effective therapeutic strategy in this subtype of tumors with poor clinical outcome." (PMID 32455819, 2020). "The results unveiled for the first time the responsible molecule Brd4 that regulates Il34 expression in cancer cells and suggested its possibility as a treatment target." (PMID 33072227, 2020). "Because BRD4 inhibitors induce apoptosis of some cancer cells, we then assessed cell cycle progression and apoptosis when BRD4 was inhibited." (PMID 32208449, 2020). "Many studies of JQ1 have focused on BRD4 inhibition because BRD4 is an appealing target in cancer treatment." (PMID 32961679, 2020). "Numerous evidences indicate that BRD4 plays an important role in the progress of haematological malignancies as well as solid tumours, indicating as a potential target for cancer therapy." (PMID 32954665, 2020). "We have also found that BRD4 is hyperphosphorylated throughout the cell cycle in many different types of cancers." (PMID 32575711, 2020). "The small molecule BRD4 inhibitors will, however, lead to feed-back BRD4 protein elevation in cancer cells, resulting in only modest anti-proliferative activity." (PMID 32163373, 2020). "Modulating the target gene expression of EMT regulators driven by PCAF–TF (ISX)–BRD4 clearly demonstrates a mechanistically synergistic regulatory effect on cancer metastasis." (PMID 31908141, 2020). "A number of studies have found that BRD4 inhibitors lead to the accumulation of BRD4 protein in cancer cells." (PMID 33093476, 2020). "Accumulating evidence indicates that BRD4 is dysregulated in numerous types of cancer and influences tumor progression." (PMID 32303673, 2020). "The level of BRD4 expression was increased in the cancerous regions, as compared to the non-cancer regions, within each individual patient." (PMID 32499570, 2020). "BRD4 regulates transcription of Myc, which in turn is involved in the progression of a variety of cancers." (PMID 32824207, 2020). "Immunomodulatory functions of BRD4 have been described for some cancers and BRD4 inhibitors epigenetically regulate selected immune cells, such as CD8 T cells." (PMID 33396954, 2020). "According to the results, Il34 expression mechanism is suggested to be regulated by Brd4 in IL-34-producing cancer cells, which is efficiently suppressed with JQ1." (PMID 33072227, 2020). "BRD-4 is expressed on cells of all tissues, and deregulation of BRD-4 has been shown to cause various diseases including cancer and fibrosis." (PMID 33796822, 2020). "The Cancer Genome Atlas (TCGA) data illustrate that BRD4 amplification occurs most frequently in HGSOC patients across all represented cancer subtypes, which implies that HGSOC patients is potential demographic that will benefit from BRD4 inhibitors." (PMID 32184777, 2020). "Blocking BRD4 interactions by small‐molecule inhibitors has been shown to effectively inhibit cell proliferation in cancers 12, 13, and many potential candidates have been devoted to human clinical trials." (PMID 31908141, 2020).
cancer (continued). "In the present study, we determined that BRD4 was upregulated whereas caspase-1 were downregulated in RCC cancer samples and cell lines." (PMID 32303673, 2020). "To model cancer suppression by these drugs, we generated BRD4- and TOP2A-degron cell lines using the HCT116 CMV-OsTIR1(F74G) background and confirmed the rapid degradation of the fusion proteins." (PMID 33177522, 2020). "Multiple small-molecule inhibitors of BRD4 have been developed, showing promising anticancer results in experimental and clinical cancer studies." (PMID 32978368, 2020). "We have recently shown that the BET protein BRD4 promotes muscle atrophy in an in vitro model of glucocorticoid-induced atrophy and in experimental models of cancer cachexia." (PMID 33257646, 2020). "Together, BRD4 inhibitor exploitation plays an important potential role in cancer therapy, especially hypoxic tumors." (PMID 33109235, 2020). "In conclusion, we identified here Brd4 as a responsible transcription regulator that controls Il34 expression in cancer cells." (PMID 33072227, 2020). "BETi clinical trials have revealed promising results, demonstrating the potential of targeting BRD4 in cancer therapy." (PMID 32575711, 2020). "Despite a greater than 10‐fold loss in binary binding affinity for Brd4, macroPROTAC‐1 exhibits rapid and potent intracellular degradation of Brd4, and cytotoxicity in BET‐sensitive cancer cell lines that are comparable to MZ1." (PMID 31746102, 2020). "Our recent studies demonstrate that the stability and functions of Brd4 are positively regulated by Pin1 in cancer cells." (PMID 32266261, 2020). "Because inhibition of BRD4 impedes growth of cancer cells, targeting BRD4 has recently emerged as a promising anticancer approach." (PMID 33072227, 2020). "It remains to be explored, if and how the misregulation of housekeeping genes affects cancer proliferation in the context of BRD4." (PMID 32382029, 2020). "Brd4 has emerged as a therapeutic target in cancer and inflammatory diseases, and there are many clinical trials with different BETi, including JQ1, for their efficacies against tumors and inflammation." (PMID 32820150, 2020). "The combinatorial inhibition of CDK1 and BRD4 has the potential to overcome the low specificity of CDK1 inhibitor as well as cancer resistance to BETi, allowing more effective killing of BRD4-driven cancer cells." (PMID 32575711, 2020). "In cancer cells, the BRD4/RelA complex avoids degradation, resulting in continuous activation of NFκB, which promotes cell proliferation." (PMID 33348732, 2020). "In contrast to noncancerous human dermal fibroblasts (HDFs), which maintain a basal level of BRD4 phosphorylation, various degrees of BRD4 hyperphosphorylation were observed in cancer cells exhibiting elevated BRD4 oncogenic activity." (PMID 32575711, 2020). "Nevertheless, based on the current data, it is questionable if BRD4 degradation is a viable therapeutic approach for targeted therapy rather than a cytotoxic treatment with a therapeutic window in aggressive cancers, similar to chemotherapy." (PMID 33371192, 2020). "Brd4 has emerged as an important factor in tumorigenesis by promoting the transcription of genes involved in cancer development." (PMID 32266261, 2020). "CDK9 was involved in cancer progression through the BRD4-dependent recruitment of p-TEFb for the transcription of the MYC gene, which is a proto-oncogene controlling cell growth and cell cycle progression." (PMID 32848135, 2020). "In several cancer types, including multiple myeloma, leukemia, and lymphoma, BRD4 has been shown to drive transcription of key oncogenes such as MYC and BCL2 by localizing to super-enhancers." (PMID 32393766, 2020).